PNPLA3 (patatin like domain 3, 1-acylglycerol-3-phosphate O-acyltransferase )
Diseases named in the same sentence as PNPLA3 in open-access papers (continued):
Sharing a sentence is not in itself a finding about the gene and the disease.
liver fibrosis (continued). "For example, the single nucleotide polymorphisms (SNPs) in phospholipase domain-containing 3 (PNPLA3) and transmembrane 6 superfamily member 2 (TM6SF2) gene have been recently associated with the development of steatosis, NAFLD-related hepatocellular carcinoma (HCC), and the stage of liver fibrosis." (PMID 34746177, 2021). "In addition, we found that the rs58542926 polymorphism of the TM6SF2 gene is associated with advanced liver fibrosis independent of rs738409 polymorphism of the PNPLA3 gene." (PMID 29258449, 2017). "Thus, we did not observe an association between PNPLA3 and advanced liver fibrosis when adjusting for other relevant factors." (PMID 26599080, 2015). "Finally, we did not confirm the reported association between PNPLA3 genotype and severity of liver fibrosis." (PMID 24498332, 2014). "PRS-5 based on variations in PNPLA3, TM6SF2, GCKR, MBOAT7, and HSD17B13 is also useful for the prediction of liver fibrosis." (PMID 40507973, 2025). "In addition, this is the first study to investigates the relationship between the rs738409 (PNPLA3), rs58542926 (TM6SF2), rs1260326 and rs780094 (GCKR), rs641738 (MBOAT7), rs72613567 (HSD17B13), and rs2642438 (MTARC1) polymorphisms in the Brazilian population with MASLD and hepatic fibrosis." (PMID 40650184, 2025). "Our results showed that PNPLA3 rs738409 C>G CG and GG genotype carriers in MASLD and liver fibrosis in MASLD cases had higher proportions than those in the controls (both p < 0.05)." (PMID 38674389, 2024). "As the severity of liver fibrosis in MASLD increased, PNPLA3 rs738409 C>G CG and GG genotype carriers in subjects had higher proportions than CC genotype carriers (p = 0.003)." (PMID 38674389, 2024). "As we mentioned, the PNPLA3 and HSD17B13 genotypes are in a mutual relationship in pathology of NAFLD, and improvement of liver fibrosis is more important than that of steatosis." (PMID 33922278, 2021). "The recent research in murine models shows that antisense oligonucleotide therapy for PNPLA3 can delay the progress of NAFLD and improve liver fibrosis." (PMID 34476007, 2021). "PNPLA3 genotype has been shown to play a significant role in NAFLD pathogenesis, progression of liver fibrosis and even in the development of HCC." (PMID 32570776, 2020). "Our first aim in this study was to evaluate and quantify PNPLA3 expression during different stages of liver fibrosis in NASH patients, according to the different PNPLA3 genotypes (WT = C/C or I148M = G/G)." (PMID 32043752, 2020). "We therefore investigated whether the presence of PNPLA3 and TM6SF2 modifies the impact of metabolic dysfunction and alcohol consumption on liver fibrosis in patients evaluated for SLD." (PMID 41492318, 2026). "Our findings indicate that PNPLA3 and TM6SF2 variants do not act as independent determinants of liver fibrosis once gene–environment interactions are considered." (PMID 41492318, 2026). "In conclusion, our findings demonstrate that genetic variants in PNPLA3 and TM6SF2 do not act as independent risk factors for liver fibrosis, but amplify the detrimental effects of metabolic dysfunction (especially insulin resistance) and alcohol consumption." (PMID 41492318, 2026). "Logistic regression analysis for the association of PNPLA3 rs738409 C>G with MASLD with liver fibrosis and MASLD without liver fibrosis was assessed." (PMID 38674389, 2024). "The proportions of cases with and without liver fibrosis in MASLD and controls in different alleles of PNPLA3 rs738409 C>G were also assessed (p < 0.001)." (PMID 38674389, 2024). "The PNPLA3 risk variant, but not the TM6SF2 genotype, was an independent risk factor for developing hepatic fibrosis among patients with NAFLD (HR 1.17, 95% CI 1.04–1.32, P = 0.010)." (PMID 36403577, 2023). "The PNPLA3 I148M variant had no significant impact on on bile composition, including UDCA content, clinical outcomes, progression of liver fibrosis, hepatobiliary cancer risk, liver transplantation, or overall survival." (PMID 36454904, 2022).
liver fibrosis (continued). "In conclusion, our results indicate that genotyping of PNPLA3 rs738409 and MBOAT7-TMC4 rs641738 could help to identify PLWHIV with NAFLD, NASH, and liver fibrosis and to optimize follow-up and treatment of diseases associated with NAFLD." (PMID 36110512, 2022). "In conclusion, the PNPLA3 rs738409 genotype is significantly related to the progression of ALD, NAFLD and HCV to liver fibrosis, and may be related to the severity of liver fibrosis." (PMID 34476007, 2021). "PNPLA3 SNP, which has the most abundant evidence, contributes not only to the development of hepatic fibrosis but also to hepatocarcinogenesis." (PMID 32785100, 2020). "These genetic variations also did not mediate the effect of PNPLA3 rs738409 SNP for liver developing liver fibrosis or liver cirrhosis." (PMID 30875804, 2019). "These genetic variations also did not mediate the effect of PNPLA3 rs738409 SNP on the development of liver fibrosis or liver cirrhosis." (PMID 30875804, 2019). "The strong association of PNPLA3 with type 4 and NASH-HCC but not with type 1 to type 3 indicates that it is involved in the later stages of NAFLD, particularly in liver fibrosis." (PMID 29385134, 2018). "The prevalence of the PNPLA3 risk allele was lower in non-Hispanic White subjects, which may have helped to account for their comparatively lower risk of NAFLD and liver fibrosis." (PMID 40964692, 2025). "Furthermore, the GG genotype of the PNPLA3 SNPs rs2896019 and rs738409 was found to be associated with ALT levels >30 U/L and was a risk factor for advanced liver fibrosis independent of cardiovascular metabolic risk factors in MASLD." (PMID 39713746, 2024). "In the present study we showed that PNPLA3 and TM6SF2 gene polymorphisms significantly increased the risk of advanced fibrosis in patients with NASH, while more importantly, IR increased the risk of advanced liver fibrosis in non-diabetic patients." (PMID 35625751, 2022). "Thus, the association is driven by the TM6SF2 rs58542926 variant, and carriage of its minor allele confers significantly greater NAFLD-related hepatic fibrosis independent of gender, age at biopsy, BMI, T2DM and PNPLA3 rs738409 genotype." (PMID 24978903, 2014). "Moreover, SNPs other than PNPLA3 were associated with hepatic lipidification but had no or very mild effects on increasing ALT levels and liver fibrosis, suggesting that they may not have been associated in this study." (PMID 39713746, 2024). "The proportions of cases with and without liver fibrosis in MASLD and controls in different genotypes of PNPLA3 rs738409 C>G were assessed (p = 0.003, FDR corrected p-value = 0.012)." (PMID 38674389, 2024).
Obesity (114 papers, 2009 to 2026). Accumulation of substantial excess body fat. "The mechanism by which PNPLA3 rs738409 G-allele carriers promote liver fat and fibrosis, in addition to their direct effects on hepatocytes or through insulin resistance and obesity, the effects via decrease of gut Feacalibacterium were suggested." (PMID 40074353, 2025). "Although ALT can be elevated in other conditions, in this Latino cohort of children with a high prevalence of obesity at high risk for the PNPLA3 I148M allele, elevated ALT values were most likely due to MASLD." (PMID 40814062, 2025). "MASLD can be due to obesity with insulin resistance and/or genetic predisposition, i.e., polymorphism in the patatin-like phospholipase domain-containing 3 (PNPLA3) gene." (PMID 40244110, 2025). "Evidence from the UK Biobank indicates that the interaction between the PNPLA3 genotype, alcohol intake, and obesity can increase the risk of HCC by up to 30 times." (PMID 40650184, 2025). "The global increase in HCC associated with MASLD is driven by the increase in metabolic diseases, with confirmed risk factors including T2D, obesity, and the patatin-like phospholipase domain-containing 3 (PNPLA3) gene variant." (PMID 40299427, 2025). "Environmental factors such as obesity and diet further amplify the risk, with obesity strengthening the association between the PNPLA3 variant and liver fat accumulation." (PMID 41303369, 2025). "The prevalence of dyslipidemia and obesity in patients with MASLD carrying the PNPLA3 variant was 60% and 30%, respectively." (PMID 39728506, 2024). "The association of MLXIPL Gln241His with SLD was more pronounced in subgroups with common SLD comorbidities and risk factors like T2D or obesity, as well as carriers of patatin-like phospholipase domain-containing protein 3 (PNPLA3) I148M." (PMID 38668731, 2024). "Fasting decreases PNPLA3 expression, while refeeding or obesity is associated with high PNPLA3 expressions." (PMID 39201329, 2024). "In Europe, individuals with the PNPLA3 GG genotype, particularly those with severe obesity, have a higher risk of developing HCC." (PMID 38784134, 2024). "Our observation was independent of risk factors of disease severity such as type-II DBT, obesity and G-allele PNPLA3." (PMID 39312529, 2024). "All this is closely related to a higher number of patients with T2DM, metabolic syndrome and obesity, in addition to a higher genetic risk related mainly with the presence of polymorphism PNPLA3 (Patatin like phospholipase domain-containing protein 3)." (PMID 37761319, 2023). "As muscle mass decreased, the risk of NAFLD increased even after adjustment for age, sex, obesity, metabolic syndrome and PNPLA3 and TM6SF2 risk alleles [hazard ratio (HR) per quartile, 1.18, 95% confidence interval (CI), 1.11–1.27, P < 0.001]." (PMID 36403577, 2023). "These words include hyperinsulinemia, glucose intolerance, hypertriglyceridemia as terms related to the claims from research performed from 2004 until 2007, that associated PNPLA3 with obesity, insulin resistance in adipose tissues, the phenotypes of NAFLD." (PMID 37225853, 2023). "Environmental risk factors, among which obesity, and genetic variations such as the I148M PNPLA3 polymorphism strongly contribute to NAFLD pathogenesis." (PMID 36937355, 2023). "We analysed the impact of obesity, diabetes mellitus and genetic risk factors (alleles of PNPLA3 or HSD17B13) on nonalcoholic steatohepatitis (NASH), significant fibrosis (stage ≥ 2) and advanced fibrosis (stage ≥ 3) in 346 patients." (PMID 36266438, 2022). "We did not observe any supramultiplicative associations between the PNPLA3 I148M variant, obesity, and alcohol intake in overall and cardiovascular disease–related deaths (eTable 4 in the Supplement)." (PMID 36190732, 2022). "All these data suggest that in addition to obesity there are also other factors possibly related to ethnicity that can modulate the effect of the PNPLA3 genetic variant on T2D risk." (PMID 33102799, 2020).
Obesity (continued). "Our present study aimed to evaluate the PNPLA3, leptin and adiponectin genes polymorphism and the irisin, leptin and adiponectin levels as significant specific biomarkers for obesity and insulin resistance in type 2 diabetes mellitus." (PMID 32544194, 2020). "A possible reason for this association is that obesity uncovers the effect of the PNPLA3 variant, increasing its effect size." (PMID 33102799, 2020). "Multiple risk factors for NASH progression have been identified, such as diet, MetS, T2DM, obesity, Hispanic ethnicity and polymorphisms in the patatin-like phospholipase domain-containing 3 (PNPLA3) gene." (PMID 32595949, 2020). "Our present study was designed to assess the potential role of irisin, adiponectin, leptin and gene polymorphism of PNPLA3, leptin and adiponectin as predictive markers of diabetes associated with obesity." (PMID 32544194, 2020). "It has been emphasized that the PNPLA3 rs738409 polymorphism interacted with obesity on the development of NAFLD." (PMID 27905898, 2016). "Aim of this study is to examine the relationship between PNPLA3 I148M genotypes and serum triglycerides, insulin resistance and T2D susceptibility by testing a gene-environment interaction model with severe obesity." (PMID 22724004, 2012). "A highly significant statistical interaction term between PNPLA3 genotype and severe obesity status was observed in determining risk of type 2 diabetes (P = 0.002)." (PMID 22724004, 2012). "Given the known association between NAFLD and insulin resistance and obesity, we also tested for an association of PNPLA3 rs139051 polymorphisms with FPG, plasma lipids and BMI." (PMID 23226254, 2012). "The results of this study are supported by extensive prior research that has established the robust gene/environment interaction between the PNPLA3 148M allele and obesity in determining individual susceptibility to hepatocyte lipid accumulation and damage." (PMID 22724004, 2012). "Genetic variants in PNPLA1 and PNPLA3 showing significant association with obesity using logistic regression." (PMID 19390624, 2009). "Two studies have demonstrated genetic association between PNPLA2 and PNPLA3 with type 2 diabetes and obesity, respectively." (PMID 19390624, 2009). "Furthermore, PNPLA3 genetic variants exerted synergistic effects with obesity and heavy alcohol consumption." (PMID 42196623, 2026). "In 414 209 individuals from UK Biobank, followed for a median time of 10.9 years, there was a synergistic interaction between PNPLA3 genotype, alcohol intake and obesity; subjects with all three 3 factors had an adjusted HCC risks 30 times higher than their counterparts without all 3 risk factors." (PMID 39412170, 2025). "To test whether our model was merely detecting general risk factors, we used our original model, which was trained by PNPLA3 I148M label, to predict various risk factor labels, such as obesity (BMI ≥ 30) and Type 2 diabetes." (PMID 40478199, 2025). "The differences among racial and ethnic groups are partially explained by obesity status, sex differences (higher rates among men), and genetic polymorphisms such as the rs738409 C/G variant in patatin-like phospholipase domain-containing 3 (PNPLA3)." (PMID 36684893, 2022). "We assessed participants in the UK Biobank on whether PNPLA3 I148M variant status could help stratify the risk of heavy alcohol drinking and obesity." (PMID 36190732, 2022). "Nonetheless, the PNPLA3 gene could manifest itself better in the company of certain predisposing factors of hepatic injury (obesity, alcohol consumption, hepatic viruses)." (PMID 34833467, 2021). "PNPLA3 rs738409 GG-genotype is related tothe reduction of triacylglycerol and cholesterol concentrations in obese or glucose uncharitable ones as a result of lowered hydrolysis of triacylglycerol and intrahepatic fat aggregation caused by obesity." (PMID 32544194, 2020).
Obesity (continued). "Secondly, a variant allele (rs738409) of PNPLA3 is increased in non-obesity patients with NAFLD; it could be seen as the independent influence factor of non-obese NAFLD population." (PMID 31399032, 2019). "Similarly, we discover PNPLA2 and PNPLA3, for which genetic variations have previously been associated with obesity and non-alcoholic fatty liver disease, as the key nodes bridging Triglyceride metabolic process cluster with central regulatory mechanisms." (PMID 25466819, 2015). "Moreover, genetic reports in Europeans indicate that obesity modifies signals arising from the genome, showing that the PNPLA3 I148M genotype association with increased alanine transferase (ALT) is greatly exacerbated in obesity." (PMID 22724004, 2012). "The methionine allele of the missense PNPLA3 SNP rs738409 (Ile148Met) has recently been associated with increased hepatic fat levels, hepatic inflammation and plasma levels of liver enzymes (traits linked to insulin resistance and obesity)." (PMID 21533024, 2011). "Finally we checked if the PNPLA3 p.I148M polymorphism remained an independent HCC risk factor when other known risk factors of HCC such as obesity, diabetes, and HBV infection were also taken into account." (PMID 22087248, 2011). "The methionine allele of the missense PNPLA3 SNP rs738409 (Ile148Met) has recently been associated with increased hepatic fat levels, hepatic inflammation and plasma levels of liver enzymes (traits often linked to insulin resistance and obesity)." (PMID 20585554, 2010). "Genetic variants in PNPLA3 have previously been associated with obesity." (PMID 19390624, 2009). "Three variants in PNPLA3 showed association with obesity (rs139051, rs12483959 and rs2072907)." (PMID 19390624, 2009). "In fact, our longitudinal investigation allowed us to describe how the evolution of the PNPLA3-associated phenotype incorporates the involvement of signs and symptoms beyond the liver, such as obesity, while other parameters might be within normal ranges thanks to the therapeutic regimen." (PMID 41157259, 2025). "Moreover, obesity was reported to be an amplifier of the genetic risk, and this effect may be mediated by insulin resistance in PNPLA3 GG carriers." (PMID 40677694, 2025). "Two recent studies observed that the PNPLA3 rs738409 GG-genotype associated with lower serum triglyceride and cholesterol levels among obese or glucose-intolerant individuals and was suggested to be a result of an obesity-driven reduced triglyceride hydrolysis and intrahepatic fat accumulation." (PMID 24563329, 2014). "Based on this concept, we have investigated for the first time if obesity degree, insulin resistance or abdominal fat might modulate the strength of the effect of PNPLA3 I148M polymorphism on liver enzymes and we have found a strong interaction between W/Hr and PNPLA3 genotype." (PMID 22140488, 2011). "In this context, the interaction between ‘traditional’ metabolic risk factors—especially obesity and T2DM—with the PNPLA3 rs738409 C > G variant can account for the observed variation in disease progression and natural contribute to MASLD heterogeneity." (PMID 39412170, 2025). "In individuals with obesity, hepatic PNPLA3 expression was notably higher in women than in men, and correlated with estrogen levels." (PMID 40677695, 2025). "Single SNP analysis supports previous literature: PNPLA3 as a major driver of liver injury, independently of obesity, and TM6SF2 impacting lipid levels." (PMID 40943344, 2025). "The clinical meaning of all these results is further enriched by the synergistic interaction existing between the PNPLA3 genotype and both alcohol intake and obesity." (PMID 39412170, 2025). "Obesity, T2DM, and patatin-like phospholipase domain-containing protein 3 (PNPLA3) variants (≥3-fold HCC risk) are key contributors." (PMID 40869400, 2025).